BRCA2 (BRCA2 DNA repair associated)
Diseases named in the same sentence as BRCA2 in open-access papers (continued):
Sharing a sentence is not in itself a finding about the gene and the disease.
breast cancer (continued). "The BRCA2 p.N3124I mutation was detected in three patients treated for breast cancer (two with luminal A or B and one with TNBC), and the BRCA2 p.R2336H mutation was detected in two unrelated probands (one TNBC patient and one healthy subject)." (PMID 30040829, 2018). "The risk of breast cancer at age 70 years in CHEK2*1100delC heterozygotes is almost as high as that for BRCA1 and BRCA2 mutation heterozygotes." (PMID 29682443, 2018). "Germline pathogenic variants in BRCA1, BRCA2 and PALB2 DNA repair genes are associated with high risk of developing breast cancer." (PMID 30410870, 2018). "They focus BRCA1/2 associated breast cancer, and make the mistake of considering the two very different forms of breast cancer associated with BRCA1 and BRCA2, respectively, to be biologically similar disorders." (PMID 28939999, 2018). "In contrast, the application of the upper age limit for triple-negative breast cancer patients of 40 years (Swedish Breast cancer group criteria for screening for mutations in BRCA1 and BRCA2) would miss several BRCA-positive cases in our cohort." (PMID 29928469, 2018). "Among the 51 patients who underwent PM, 6 had specimens in which occult breast cancer was found, including 1 with a BRCA1 mutation and 5 with BRCA2 mutations." (PMID 30203341, 2018). "Louis laboratories, in relation to a collaborative sequencing project on the breast cancer gene, BRCA2 (Waterston to authors Feb 2017)." (PMID 30390178, 2018). "The tumor suppressor genes breast cancer 1 (BRCA1) and breast cancer 2 (BRCA2) are key players in DNA damage response and homologous recombination (HR), which are critical for the repair of DNA double-strand breaks to maintain the fidelity of the genome." (PMID 29718910, 2018). "In carriers of breast cancer susceptibility genes 1 and 2 (BRCA1/BRCA2) mutations, pregnancy also increases the risk of breast cancer." (PMID 30202672, 2018). "The distribution of BRCA1/2 mutations identified differed by breast cancer subtype, with BRCA1 mutations predominated among TNBC (94%, 15/16) while BRCA2 mutations predominated among patients with HR and/or HER2-positive MBC (75%, 12/16)." (PMID 30318518, 2018). "Segregation analyses studies have demonstrated that risk prediction models that allow for genes to modify effect on breast cancer risk in BRCA1 and BRCA2 mutation carriers fit significantly better to familial data than models without a modifying component." (PMID 29422015, 2018). "The data from earlier studies suggested that prophylactic oophorectomy was associated with a significant 51% (95% CI 0.37–0.65) reduction in breast cancer risk for both BRCA1 and BRCA2 mutation carriers." (PMID 30572612, 2018). "Other studies with retrospective follow-up of 13 to 14 years revealed a 90% reduction of breast cancer risk in women with BRCA1 and BRCA2 mutations who underwent bilateral total mastectomy." (PMID 29713580, 2018). "Pathogenic variants in highly penetrant hereditary breast cancer genes, such as BRCA1 and BRCA2 are known to account for 5–10% of breast cancer in the general population." (PMID 30287823, 2018). "The prevalence of BRCA mutations varies in different Asian cohorts, with 21.7% (BRCA1 9.3%; BRCA2 12.4%) in patients with family history of breast or ovarian cancer in Korea and 17% (BRCA1 11%; BRCA2 6%) in Malaysian patients with early onset of breast cancer." (PMID 29861850, 2018). "In patients with BRCA1- and BRCA2-positive breast cancer, ovarian cryopreservation appears to be possible." (PMID 29177593, 2018). "F112 discusses more specific genetic risks of breast cancer (BRCA1 or BRCA2 positive), while F47 (similarity 92%) chats about more general risks." (PMID 30497991, 2018). "According to the most recent meta-analysis, the cumulative breast cancer risk by age 70 years was estimated to be 55% (95% CI: 50-59%) and 47% (95% CI: 42-51%) for Caucasian women carrying a BRCA1 or BRCA2 mutation respectively." (PMID 29861850, 2018).
breast cancer (continued). "Statistically, approximately 5–10% of all breast cancers in women are due to mutations in BRCA1 and BRCA2 genes." (PMID 30373614, 2018). "When we examined the age at diagnosis of breast cancer by gene, we found that the patients with pathogenic variants in PTEN, BRCA1, and BRCA2 were significantly younger at diagnosis compared to patients without pathogenic variants." (PMID 30287823, 2018). "Previous studies demonstrated the requirement of the FA pathway and other HDR proteins, such as Rad51 and the breast cancer susceptibility proteins BRCA1 and BRCA2, for the protection of stalled forks against nascent DNA degradation." (PMID 30422114, 2018). "Future studies should seek to evaluate whether rs1799950, and other common BRCA1 and BRCA2 variants, modulate sensitivity to platinum and other DNA damaging agents in vitro, and address whether such variants convey inherited susceptibility to malignancy, particularly to OC and breast carcinoma." (PMID 29298688, 2018). "Based on the roles of PARP1, γH2AX, BRCA1, and BRCA2 in DNA damage repair, the combined expression patterns were evaluated in breast carcinoma and soft tissue sarcomas." (PMID 29784019, 2018). "In a previous association study, the BRCA mutations were found in about 20% of all hereditary breast cancers and women carrying BRCA1 and BRCA2 mutation were easily caught up with breast cancer." (PMID 28982360, 2017). "For example, breast cancer screening is recommended for BRCA1/BRCA2-positive men, beginning at age 35, and increased colon surveillance is recommended for CHEK2-positive individuals." (PMID 28008555, 2017). "There was marginal evidence of an interaction between the breast cancer risk PRS and class 2 mutations in BRCA2 mutation carriers (P = 0.03, with a slightly higher HR estimate for the PRS for class 2 mutation carriers)." (PMID 28376175, 2017). "We analysed primary mutation screens on women with breast cancer with unequivocal HER2 overexpression and assessed the likelihood of BRCA1/BRCA2 mutations by age, oestrogen receptor status and Manchester score." (PMID 27796713, 2017). "This information was already reported by the Breast Cancer Linkage Consortium in BRCA2 carriers with a large analysis conducted in SEER database." (PMID 28559958, 2017). "BRCA2/1991del4 was identified in four breast cancer patients and ex1-14del in two breast cancer patients." (PMID 28680148, 2017). "Recent studies demonstrate that genetic predispositions for familial breast cancer can be ethnic-specific, as well exemplified by the different spectrum of germline mutation in BRCA1 and BRCA2 between different ethnic populations." (PMID 28076423, 2017). "For breast cancer in BRCA2 carriers, the highest values for Harrell's c were achieved by the population-based overall and ER-positive breast cancer PRSs (c = 0.56, 95% CI = 0.55 to 0.58, in each case)." (PMID 28376175, 2017). "We thus studied the impact of acetaldehyde on the viability of Brca2‐deleted (KB2P3.4) mouse mammary tumor cell lines, relative to Brca2 wild‐type controls (KB2P3.4R3)." (PMID 28729482, 2017). "That patient was BRCA1 and BRCA2 WT and had a personal history of bilateral breast cancer (diagnosed at 37 and 41 years old), both tumors were invasive ductal carcinomas with estrogen receptor negative." (PMID 27926510, 2017). "Of the evaluated breast cancer cell lines with mutations in BRCA1 (MDA-MB-436 and HCC-1937) or BRCA2 (HCC-1569, BT-20, BT-474, MDA-MB-361), only one (HCC-1569) was found to respond to BMN-673." (PMID 28649435, 2017). "We used the updated ER-negative PRS to predict breast cancer risk for BRCA1 carriers and the updated overall breast cancer PRS to predict breast cancer risk for BRCA2 carriers." (PMID 28376175, 2017). "Efforts have been made to study genetic predisposition for Egyptian familial breast cancer, mostly focused on BRCA1 and BRCA2, but comprehensive data at genomic level from local patients are lacking." (PMID 28076423, 2017).
breast cancer (continued). "Mutation screening of the breast cancer genes BRCA1 and BRCA2 identifies a large fraction of variants of uncertain clinical significance (VUS) whose functional and clinical interpretations pose a challenge for genomic medicine." (PMID 28339459, 2017). "In about 5–10%, breast cancer occurs in a hereditary setting, most commonly due to BRCA1 or BRCA2 germline mutations, which lead to a 40–80% lifetime risk of developing breast cancer as well as a 30–40% lifetime risk of ovarian cancer development." (PMID 28569220, 2017). "Song reported that the variant ratio of BRCA1 and BRCA2 in Shanghai was 11.4% and 2.9%, respectively, whereas in our study the variant ratio of BRCA1 and BRCA2 in breast cancer patients were 2.5% and 7.5%, respectively." (PMID 29093764, 2017). "Known genetic factors contributing to a higher lifetime risk of breast cancer comprise rare variants in BRCA1, BRCA2, PALB2, ATM and CHEK2." (PMID 28199975, 2017). "Recently a panel of BRCA1 and BRCA2, HISPANEL has been constructed with diverse mutations from Hispanic breast cancer women from USA, based on the information in manuscripts describing mutations in BRCA1 and BRCA2 from Latin American countries and data bases." (PMID 29088781, 2017). "In spite of the big boost in breast cancer danger linked with BRCA1 and BRCA2 genes, they are responsible approximately 5% of all breast cancers, as merely 1 in 1000 females have acquired one of them." (PMID 28969709, 2017). "Similar phenotypes were observed in Brca2-null mouse mammary tumour cells, expressing GFP-tagged Histone-H2B and mCherry-tagged α-Tubulin." (PMID 28714471, 2017). "The crucial role of the breast cancer susceptibility proteins, BRCA1 and BRCA2 in the DNA repair has been known since 1995." (PMID 28055979, 2017). "The mutated tumor suppressor gene, PALB2 largely affects BRCA2, which increase the risk of BRCA1/2 based breast cancer." (PMID 28477017, 2017). "There were 1134 women with breast cancer with verified HER2 and ER status who had undergone full mutation screening of BRCA1 and BRCA2." (PMID 27796713, 2017). "The benefit of BRCA1 or BRCA2 genotyping in newly diagnosed breast cancer patients is increasingly evident." (PMID 28120249, 2017). "The three main breast cancer PRSs that were constructed on the basis of associations with female breast cancer risk were strongly associated with male breast cancer risk for both BRCA1 and BRCA2 mutation carriers." (PMID 28448241, 2017). "The breast cancer susceptibility proteins BRCA1 and BRCA2 have emerged as key stabilizing factors for the maintenance of replication fork integrity following replication stress." (PMID 29038425, 2017). "Survival assays confirmed the sensitivity of both Brca1‐ and Brca2‐deleted mouse mammary tumor‐derived cells lines to acetaldehyde." (PMID 28729482, 2017). "Within breast cancer patients, approximately 10% are heterozygous mutation carriers of the BRCA1/BRCA2/PALB2 gene, and their cancer resulted from the loss of heterozygosity." (PMID 29023372, 2017). "Our data suggests that BRCA2 p.Ile3412Val is likely to be benign and BRCA1 p.Arg762Ser is likely to be associated with breast cancer risk." (PMID 28222693, 2017). "As a proof of concept, known breast cancer-predisposing genes like BRCA1, BRCA2, and CHEK2 were selected by our procedure." (PMID 28569218, 2017). "More than 25 breast cancer susceptibility genes have been identified so far, most of which play a role in the DNA repair pathway linked to BRCA1 and BRCA2." (PMID 28339459, 2017). "Breast cancer, of which heredity explains approximately 10–15% of the cases, with only 5% can be clarified by known genetic polymorphisms such as BRCA1 and BRCA2." (PMID 28074086, 2017). "Retrospective studies, suggest an estimated cumulative risk of breast cancer to 70 years of age of 40–87% for BRCA1 carriers and 27–84% for BRCA2 carriers." (PMID 28985766, 2017).
breast cancer (continued). "Breast cancer risk increases dramatically in women carrying mutations in a breast cancer susceptibility gene, most frequently BRCA1 or BRCA2." (PMID 28977823, 2017). "Women who are heterozygous for a BRCA1 or BRCA2 pathogenic variant have up to an 80% risk of developing breast cancer by age 90; and an ovarian cancer risk of about 55% with BRCA1 mutations and 25% with BRCA2 mutations." (PMID 28751759, 2017). "Nine genes in this module – Akt1, Brca2, Ccnd1, Dnmt1, Mki67, Palb2, Rrm1, Timeless, and Top2a – are known human breast cancer genes according to the MalaCards database; four of them are hub genes." (PMID 28212608, 2017). "We found similar results in the GSE19177 dataset which contains expression profiles for 19 BRCA1, 30 BRCA2 and 25 non-BRCA1/2 mutation familial breast cancer samples." (PMID 29146938, 2017). "In the largest follow-up study of BRCA-mutated patients in the Hereditary Breast Cancer Study Group, eight new cases of pancreatic cancer were identified, out of 5089 women, in the database of BRCA1 and BRCA2 carriers, versus 3.28 expected pancreatic cancers." (PMID 29069866, 2017). "Linkage analysis followed by positional cloning has been successfully applied to identify the high penetrance breast cancer susceptibility genes BRCA1 and BRCA2." (PMID 29262523, 2017). "Breast cancer susceptibility genes 1 and 2 (BRCA1 and BRCA2) mutations are associated with hereditary breast and ovarian cancer syndromes (HBOC)." (PMID 28706762, 2017). "In the TCGA breast cancer data, 13 and 14 samples contain at least one somatic mutation in BRCA1 and BRCA2, respectively." (PMID 29146938, 2017). "Twenty years ago two genes, BRCA1 (MIM: 113705) and BRCA2 (MIM: 600185), which mutations confer a high risk to breast cancer were identified in families having four or more relatives with breast or ovarian cancer." (PMID 29088781, 2017). "In this study, we assessed the preferences for breast cancer risk-reduction treatments among women with germline BRCA1 and/or BRCA2 mutations." (PMID 28624978, 2017). "Evidence of association with breast cancer risk (at p < 10−2) was observed for nine SNPs in BRCA1 mutation carriers and three SNPs in BRCA2 mutation carriers." (PMID 27796716, 2017). "Approximately 5–10% of all of breast and ovarian cancer cases reflect inherited genetic defects primarily in two well-known high-penetrance breast and ovarian cancer genes, BRCA1 (breast cancer 1, early onset) and BRCA2 (breast cancer 2, early onset)." (PMID 28738860, 2017). "Identified risk factors for CBC include young age at first breast cancer diagnosis, breast cancer family history, mutations in BRCA1 and BRCA2 (BRCA1/2), young age at menarche, nulliparity, and obesity." (PMID 28724391, 2017). "Most known cancer syndromes were first found to be associated with an increased risk of one tumor type such as breast cancer (BRCA1 and BRCA2) or colorectal cancer (APC and the DNA mismatch repair genes)." (PMID 29299148, 2017). "There was evidence for a PRSxage interaction for the ER-negative breast cancer PRS for BRCA1 carriers (P = 3×10−6) and for the overall breast cancer PRS for BRCA2 carriers (P = .01)." (PMID 28376175, 2017). "Further supporting the clinical relevance of our findings, acetaldehyde treatment specifically inhibited growth of BRCA2‐deficient human tumors in xenograft models and PARP inhibitor‐resistant BRCA1‐deficient allografted mammary tumors." (PMID 28729482, 2017). "Many genes involved in DNA repair and cell cycle have been linked with breast cancer, including the genes BRCA1 and BRCA2 which direct DNA double-stranded break by homologous recombination." (PMID 29291027, 2017). "Mutations in the breast cancer genes BRCA1 and BRCA2 increase the risks to breast cancer, and BRCA1 and BRCA2 proteins act as tumor suppressor genes." (PMID 28938549, 2017). "Cumulative lifetime breast cancer risks for male BRCA1 and BRCA2 pathogenic variant carriers are 1–2 and 5–10%, respectively." (PMID 28008555, 2017).
breast cancer (continued). "For instance, knockdown of BRCA2 in breast cancer cell lines modulated expression of RXR isoforms in opposing ways and knockout of BRCA1 reduced expression of PPARγ in cardiomyocytes." (PMID 28427429, 2017). "We detected several expected variants on known breast cancer-predisposing genes like BRCA1 and BRCA2, which are a confirmation of the validity of this study." (PMID 28569218, 2017). "About 10% of breast cancers are hereditary and can be attributed to germline mutations in breast cancer susceptibility genes, in particular BRCA1 and BRCA2 (BRCA1/2)." (PMID 28680148, 2017). "Anytime use of diagnostic chest X-rays before the age of 50 years in women carrying the BRCA1/2 gene mutations is associated with an increased risk of breast cancer (BRCA1 OR = 1.16; 95% CI = .64–2.11; BRCA2 OR = 1.22; 95% CI = .62–2.42)." (PMID 28865460, 2017). "We have shown that splicing reporter minigenes of the breast cancer genes BRCA1 and BRCA2 are useful tools to functionally test DNA variants." (PMID 28339459, 2017). "We found that having Asian ancestry, a prior history of breast cancer, and a BRCA1 or BRCA2 mutation all appear to be positively associated with TNBC." (PMID 28912973, 2017). "In Chile, our group has screened BRCA1 and BRCA2 genes in 336 patients with a family history of breast cancer and 117 patients unselected for family history, recruited throughout the country." (PMID 29088781, 2017). "Since then, the screening of BRCA1 and BRCA2 has been performed in multiple populations across the world revealing that 10 to 50% of breast cancer patients with family history of breast and/or ovarian cancer carry a BRCA1 or BRCA2 mutation." (PMID 29088781, 2017). "Similar results were obtained upon depletion of BRCA1 or BRCA2 in BT-549 breast cancer cells treated with olaparib." (PMID 28714471, 2017). "Germline pathogenic variants in the tumor suppressor genes BRCA1 (MIM# 113705) and BRCA2 (MIM# 600185) are associated with increased risk of breast and ovarian cancer, and account for about 16% of the familial risk for breast cancer." (PMID 28339459, 2017). "Germline mutations in the BRCA2 gene are a risk factor for both male and female breast cancer, but mutations in the BRCA1 gene appears to be a risk much more for female breast cancer than for male breast cancer." (PMID 27286002, 2017). "Several susceptibility genes have been established for female breast cancer, of which mutations in BRCA1 and especially in BRCA2 are also known risk factors for male breast cancer (MBC)." (PMID 28874143, 2017). "Of these, 1826 patients had sporadic breast cancer, 33 had BRCA-positive cancer (19 BRCA1-mutated and 14 BRCA2-mutated) and 66 had BRCA-wild type breast cancer." (PMID 27899083, 2016). "Breast cancer patients with family histories of ovarian cancer exhibited the highest overall mutation rate of BRCA1 and BRCA2, which implied that BRCA1 and BRCA2 mutations are more likely to occur in families with a history of both breast and ovarian cancer." (PMID 26852015, 2016).